SEMA3D (semaphorin 3D)
Description:
Induces the collapse and paralysis of neuronal growth cones. Could potentially act as repulsive cues toward specific neuronal populations. Binds to neuropilin (By similarity).
Synonyms: coll-2; Sema-Z2
Tractability: Antibody: UniProt places it where antibodies can reach, with medium confidence; UniProt predicts a signal peptide or a membrane-spanning region; its Gene Ontology location is reachable by antibodies, with medium confidence.
Gene: Protein-coding gene on chromosome 7 (84,995,195 to 85,187,056, reverse strand). Ensembl gene ENSG00000153993.
Subcellular location: Secreted
Subcellular location (Human Protein Atlas): Vesicles; Predicted to be secreted
Gene Ontology:
Molecular function: chemorepellent activity; neuropilin binding; semaphorin receptor binding
Biological process: axon guidance; negative chemotaxis; neural crest cell migration; positive regulation of cell migration; semaphorin-plexin signaling pathway; forebrain development
Cellular component: plasma membrane; extracellular region
Genetic constraint (gnomAD): Loss-of-function variants: 34 observed, 42.15 expected, observed/expected ratio (o/e) 0.81, 90% interval 0.61 to 1.07. The upper end of that interval is the gene's LOEUF score, 1.07, which puts it in group 4 of 6, group 1 being the genes least tolerant of losing a copy. Missense variants: 430 observed, 474.87 expected, observed/expected ratio (o/e) 0.91, 90% interval 0.84 to 0.98. Synonymous variants: 161 observed, 169.5 expected, observed/expected ratio (o/e) 0.95, 90% interval 0.83 to 1.08.
Homologues: Orthologues: chimpanzee SEMA3D (99% identical), macaque SEMA3D (99% identical), dog SEMA3D (96% identical), pig SEMA3D (96% identical), rabbit SEMA3D (95% identical), mouse Sema3d (93% identical), rat Sema3d (92% identical), guinea pig SEMA3D (86% identical), tropical clawed frog sema3d (76% identical), zebrafish sema3d (62% identical). Paralogues in human: SEMA3A (53% identical), SEMA3E (44% identical), SEMA3B (44% identical), SEMA3F (44% identical), SEMA3G (43% identical), SEMA3C (42% identical), SEMA4G (29% identical), SEMA4C (29% identical), SEMA4D (29% identical), SEMA6D (28% identical), SEMA6A (27% identical), SEMA5B (27% identical), and 7 more.
Diseases named in the same sentence as SEMA3D in open-access papers:
SEMA3D is named in the same sentence as 47 diseases in open-access papers, as found by Europe PMC text mining. Sharing a sentence is not in itself a finding about the gene and the disease. The quoted sentences say what the papers report.
glioma (5 papers, 2008 to 2025). A benign or malignant brain and spinal cord tumor that arises from glial cells (astrocytes, oligodendrocytes, ependymal cells). "Several studies have determined the role of SEMA3D in the predisposition to several type of cancers, including breast cancer, glioma, and thyroid cancer." (PMID 34573430, 2021). "In contrast, we observed that SEMA3D was statistically more expressed in low-grade than in high-grade gliomas, suggesting that its loss is involved in tumour progression to high grades." (PMID 18781179, 2008). "Irradiation and Atm loss were associated with changes in the expression of semaphorin genes specifically, semaphorin 6A (Sema6a) and semaphorin 3D (Sema3d) which have been implicated in the tumor cell proliferation and survival in glioma mouse models and in glioblastomas." (PMID 40244686, 2025). "Another study showed that the expression of SEMA3D was lower in high-grade gliomas compared with low-grade gliomas, which suggests that SEMA3D functions as a tumor suppressor in gliomas." (PMID 28320475, 2017). "Statistical analysis indicated that SEMA3B, SEMA3G and NRP2 expressions were related to prolonged survival and that SEMA3D expression was reduced in high-grade as compared with low-grade gliomas." (PMID 18781179, 2008). "SEMA3D expression was reduced in high-grade as compared with low-grade gliomas and the opposite was seen for VEGF expression." (PMID 18781179, 2008). "In addition, SEMA3D expression was reduced in high-grade as compared with low-grade gliomas." (PMID 18781179, 2008). "The RTK ligands including EFNB2, SEMA3D, PDGFA, SEMA3A and FGF14 were amplified in ~5% of the RMPAhigh gliomas." (PMID 27385209, 2016). "One can speculate that SEMA3D and SEMA3G could have similar properties and behave like anti-angiogenic proteins in gliomas." (PMID 18781179, 2008). "Moreover, to our knowledge, SEMA3D, SEMA3E, SEMA3F and SEMA3G expressions in human gliomas were not studied." (PMID 18781179, 2008).
Hirschsprung disease (5 papers, 2017 to 2023). Hirschsprung disease (HSCR) is a congenital intestinal motility disorder that is characterized by signs of intestinal obstruction due to the presence of an aganglionic segment of variable extent in the terminal part of the colon. "Some research showed that Sema3D was correlated with familial Meniere disease, development of epicardium, and Hirschsprung disease." (PMID 35813868, 2022). "In addition, two studies reported that SEMA3D plays a crucial role during the development of the enteric nervous system, and that abnormal SEMA3D pathway may lead to the occurrence of Hirschsprung’s disease." (PMID 28320475, 2017). "Both the mRNA and protein levels of SEMA3D involved in the abnormality of ANS and aganglionic megacolon increased significantly in iCD." (PMID 37727374, 2023). "Notably, SEMA3D emerged as the top-ranking gene among the top 20 core enrichment genes in both ANS abnormality and aganglionic megacolon gene sets." (PMID 37727374, 2023).
glioblastoma (4 papers, 2012 to 2025). The most malignant astrocytic tumor (WHO grade IV). "For example SEMA3D and SEMA3E displayed strong inhibitory effect on the glioblastoma cells whereas SEMA3A and SEMA3B expression just caused persistent cell shape contraction." (PMID 25961819, 2015). "It was demonstrated that expression of SEMA3A, SEMA3D, and SEMA3F proteins significantly inhibited angiogenesis process and the formation of subcutaneous tumors derived from glioblastoma cells U87MG." (PMID 33036421, 2020). "Sema3D and sema3E displayed the strongest inhibitory effects and their expression in U373MG or in U87MG glioblastoma cells implanted in the brains of mice prolonged the survival of the mice by more then two folds." (PMID 22936999, 2012). "To determine the effects of sema3E and sema3D expression in glioblastoma cells on the survival of tumor bearing mice, we implanted control U87MG cells or cells expressing either sema3D or sema3E in the brain cortex of mice and monitored tumor development and mouse survival." (PMID 22936999, 2012).
asthma (3 papers, 2021 to 2025). "Genetic variants in SEMA3D are associated with asthma attacks in children cohorts and this result was replicated in an adult biobank population." (PMID 33925009, 2021). "SEMA3D also plays a vital role in the lung in angiogenesis, the formation of airways, and the development of asthma." (PMID 40725399, 2025). "Accumulating evidence shows that ITGB4, SEMA3D, FCAR (Fc fragment of IgA receptor), KIT (KIT proto-oncogene, receptor tyrosine kinase), PGLYRP1, IL17RB, BIRC5 and PTGS1 are associated with prognosis in asthma." (PMID 36837510, 2023).
breast carcinoma (3 papers, 2008 to 2021). "We found that MDA-MB-231 breast cancer derived cells express predominantly np1, a receptor for sema3A and sema3D, but very little np2 if at all." (PMID 18818766, 2008). "Thus, the concentration of recombinant sema3D found in the conditioned medium of either MDA-MB-231 breast cancer cells or in MDA-MB-435 melanoma cells was significantly lower than the concentrations of sema3F or sema3G." (PMID 18818766, 2008).
lymph node metastasis (3 papers, 2017 to 2022). "The expression of SEMA3D protein was linked to lymph node metastasis, and low expression led to lymph node metastasis (χ2 = 8.415, P = 0.004)." (PMID 28320475, 2017). "To describe the impact on the prognosis of Sema3D expression in localized ccRCC, we conducted a subgroup analysis by excluding the locally advanced and metastatic patients (T3 grade, lymph node metastasis, and distant metastasis)." (PMID 35813868, 2022). "Univariate analysis also revealed that SEMA3D expression was inversely correlated with lymph node metastasis." (PMID 28320475, 2017). "SEMA3D expression was inversely correlated with lymph node metastasis, and patients with low SEMA3D expression were prone to lymph node metastasis." (PMID 28320475, 2017). "However, lymph node metastasis was negatively correlated with the expression of SEMA3D (χ2 = 8.415, P = 0.004); patients expressing only low levels of SEMA3D were prone to lymph node metastasis." (PMID 28320475, 2017). "SEMA3D levels were negatively correlated with lymph node metastasis." (PMID 28320475, 2017).
metastatic tumors (3 papers, 2015 to 2022). "We found that Sema3d is low expressed in metastatic tumor and early recurrence (<2 years) of HCC tissues but relatively high expressed in late recurrence (>2 years) and nonrecurrence (in 60 months after surgery) of HCC tissues." (PMID 35957887, 2022). "Consistent with our immunoblotting observations under ex vivo and in vivo conditions, MEGF10, KRTAP1-1, SEMA3D, MYC, and GRB10 IHC staining revealed relatively strong positivity in metastatic tumors." (PMID 26148557, 2015).
pancreatic ductal adenocarcinoma (3 papers, 2017 to 2023). An infiltrating adenocarcinoma that arises from the epithelial cells of the pancreas. "The high expression of SEMA3D, an axon guidance molecule, was found to be correlated with the PNI of pancreatic ductal adenocarcinomas (PDA), and knockdown of SEMA3D significantly inhibited the metastasis of orthotopic PDA cells in mice." (PMID 36039037, 2023). "In pancreatic ductal adenocarcinoma (PDA), AnxA2 can promote the secretion and thereby increase the levels of SEMA3D, and primary PDA patients that express high levels of SEMA3D have a wider range of metastases than those who express lower levels of SEMA3D." (PMID 28320475, 2017).
thyroid cancer (3 papers, 2017 to 2021). "In addition, hsa-mir-375 was inferred to be significant for patients’ survival with 34 associated ceRNAs, among which RUNX2, DUSP6 and SEMA3D are known oncogenes regulating cellular proliferation and differentiation in thyroid cancer." (PMID 29351231, 2018). "Another recent study showed that the expression of SEMA3D was low in thyroid carcinoma, and concluded that it could be used as a good diagnostic marker of cytologically indeterminate thyroid cancers." (PMID 28320475, 2017).
clear cell renal cell carcinoma (2 papers, 2021 to 2022). "However, the relationship between Sema3D and clear cell renal cell carcinoma (ccRCC) is barely reported and remains unclear." (PMID 35813868, 2022).
neuroblastoma (2 papers, 2020 to 2023). Neuroblastoma (NB) is the most common solid, extracranial childhood tumor. "SEMA3D upregulation has been documented in metastatic neuroblastomas and was shown to affect neuroblastoma cell migration." (PMID 37528411, 2023). "While Pea3 upregulates transcription of Sema3D and represses Sema5B, for example, Erm and Er81 upregulate Sema5A and Er81 regulates Unc5C and Sema4G while repressing EFNB3 in SH-SY5Y neuroblastoma cells." (PMID 33097800, 2020).
bladder cancer (1 paper, 2022). "Although one study indicated that samples of bladder cancer downregulated by Sema3D had a good overall survival prognosis, more studies tended toward the tumor suppressive role of Sema3D by experiment validation." (PMID 35813868, 2022).
brain tumors (1 paper, 2012). "Of the 14 mice that were inoculated with either sema3E or sema3D expressing cells only one from each group developed a brain tumor while all the mice that received control cells had tumors." (PMID 22936999, 2012). "Indeed, expression of recombinant sema3D and sema3E in U373MG cells also inhibited very strongly the development of tumors from these cells following their implantation in the brain cortex, suggesting that the effects of the semaphorins on the development of brain tumors may be general." (PMID 22936999, 2012).
cerebral tumor (1 paper, 2012). "As a result of the combined subcutaneous and intra-cerebral tumor experiments we concluded that sema3E and sema3D may represent the most potent inhibitors, so we used only these two semaphorins in subsequent experiments." (PMID 22936999, 2012).
CHARGE syndrome (1 paper, 2012). CHARGE syndrome is a multiple congenital anomaly syndrome characterized by the variable combination of multiple anomalies, mainly Coloboma; Choanal atresia/stenosis; Cranial nerve dysfunction; Characteristic ear anomalies (known as the major 4 C's). "One overlapped three exons of the SEMA3D gene coding for semaphorin 3D and the other overlapped the first intron of the SEMA3E gene, previously associated with CHARGE syndrome." (PMID 22912587, 2012).
cognitive decline (1 paper, 2023). "Our findings provide another piece of evidence to support high expression of Sema3D in the brain as a risk factor for cognitive decline." (PMID 37316917, 2023).
Cognitive impairment (1 paper, 2023). Abnormal cognition is characterized by deficits in thinking, reasoning, or remembering. "A rescue study was conducted to further establish the causal relationship between Sema3D and cognitive impairment." (PMID 37316917, 2023). "Taken together, the results from histological examination and behavioral tests suggest that Sema3D is a cause for cognitive impairment and neurodegeneration; furthermore, suppression of Sema3D possesses potential in treatment for dementia." (PMID 37316917, 2023). "Through a series of molecular studies, animal behavior tests, comparisons of lifespan and analysis of data on human gene expression in the brain, we concluded that cerebral Sema3D is a novel risk factor for neurodegeneration and cognitive impairment." (PMID 37316917, 2023). "We first demonstrated the protective role of miR-195 in cognitive functions then we identified Sema3D as a direct target of miR-195 and also a key contributor to neurodegeneration and cognitive impairment." (PMID 37316917, 2023). "The present study revealed Sema3D is a potential target for cognitive impairment." (PMID 37316917, 2023). "Furthermore, we developed a novel small molecule to demonstrate that Sema3D can be a druggable target, which sheds light on new prevention and treatment of cognitive impairment." (PMID 37316917, 2023).
colon cancer (1 paper, 2008). "Also, SEMA3D (cell differentiation) was highly up regulated in MG-thymoma but not colon cancer." (PMID 18545673, 2008).
dementia (1 paper, 2023). Loss of intellectual abilities interfering with an individual's social and occupational functions. "Collectively, these results provided another line of evidence supporting the association between Sema3D and dementia." (PMID 37316917, 2023). "Analyzing human brain data also supported that a high level of Sema3D was associated with dementia." (PMID 37316917, 2023). "Although the hippocampus is often damaged in the early stage of dementia, other brain regions also become involved as the disease progresses; accordingly, we analyzed Sema3D levels in both hippocampus and neighboring brain regions." (PMID 37316917, 2023). "According to the GEO datasets, we found that Sema3D mRNA levels were significantly increased with the severity of dementia in the hippocampus, prefrontal cortex, visual cortex and cerebellum." (PMID 37316917, 2023). "More importantly, analysis of the data on the Gene Expression Omnibus database showed that Sema3D levels were significantly higher in dementia patients than normal controls (p < 0.001)." (PMID 37316917, 2023). "Histological staining revealed an age-dependent increase of Sema3D; then, we tested for potential correlation between the brain Sema3D level and dementia using the NCBI Gene Expression Omnibus (GEO) database." (PMID 37316917, 2023). "Taken together, these data indicated that a high Sema3D level is a common characteristic in dementia patients and also in normal aging subjects, which suggest Sema3D as a contributor to the development of dementia and brain aging." (PMID 37316917, 2023). "Among the three AD datasets, hippocampal Sema3D levels were significantly higher in the subjects with more severe AD in two datasets (GSE1297 and GSE48350) while also being higher in subjects with more severe clinical dementia (GSE84422) and FTLD-U (GSE13162)." (PMID 37316917, 2023). "As such, the current data on small molecules interfering with Sema3D signaling has only demonstrated that continuous endeavor in discovering Sema3D inhibitors for dementia treatment is worthwhile, although we did not explore Sema3D co-receptors because this was beyond the scope of the present work." (PMID 37316917, 2023).
dysautonomia (1 paper, 2023). An acute or chronic disorder, affecting the sympathetic or parasympathetic nervous system. "The identified genes, including SEMA3D and PDE1A, may serve as potential diagnostic biomarkers for differentiating between CD and UC, as well as therapeutic targets for restoring enteric dysautonomia and SMC proliferative disorders in CD." (PMID 37727374, 2023).
hepatocellular carcinoma (1 paper, 2022). A malignant tumor that arises from hepatocytes. "Sema3d restrained the progression of hepatocellular carcinoma proliferation, invasion, and metastasis through inactivating Pi3k/Akt, which may serve as a novel prognostic predictor and a potential therapeutic target for HCC patients." (PMID 35957887, 2022). "Our data showed that Sema3d restrained hepatocellular carcinoma proliferation, invasion, and metastasis through inactivating Pi3k/Akt via interaction with FLNA, which may serve as a novel prognostic predictor and a potential therapeutic target for HCC patients." (PMID 35957887, 2022). "However, the function of Sema3d in hepatocellular carcinoma (HCC) remains elusive." (PMID 35957887, 2022).
osteoarthritis (1 paper, 2022). A noninflammatory degenerative joint disease occurring chiefly in older persons, characterized by degeneration of the articular cartilage, hypertrophy of bone at the margins and changes in the synovial membrane. "SEMA3D is a member of the class III semaphorin family and is a marker of osteoarthritis." (PMID 36133435, 2022).
pancreatic cancer (1 paper, 2025). "Sema3d has been recently shown to promote pancreatic cancer progression by stimulating macrophage polarisation into a protumourigenic M2 phenotype." (PMID 40993705, 2025).
renal fibrosis (1 paper, 2026). A final common manifestation of a wide variety of chronic kidney diseases characterized by glomerulosclerosis and tubulointerstitial fibrosis. "Systemic administration of Sema3d-shRNA using adeno-associated virus serotype 9 (AAV9) effectively reduced Sema3d levels and significantly alleviated renal fibrosis in mice." (PMID 41608631, 2026). "This study reveals new target for mitigating renal fibrosis and microvascular loss, suggesting that targeting the Sema3d signaling pathway may provide a novel strategy for preventing AKI fibrotic progression." (PMID 41608631, 2026).
schizophrenia (1 paper, 2018). A major psychotic disorder characterized by abnormalities in the perception or expression of reality. "On the other hand, non-synonymous variations in the Sema3D gene had a significant protective effect against developing schizophrenia." (PMID 30063210, 2018).
Stroke (1 paper, 2025). Sudden impairment of blood flow to a part of the brain due to occlusion or rupture of an artery to the brain. "Indeed, we see by ELISA of leptomeningeal lysates that semaphorin 3a (Sema3a), but not semaphorin 3d, is specifically decreased in WT, but not Mrgprb2−/− mice after stroke." (PMID 40712576, 2025).